CD40 (CD40 molecule)
Diseases named in the same sentence as CD40 in open-access papers (continued):
Sharing a sentence is not in itself a finding about the gene and the disease.
tumor (continued). "We hypothesized that adding activation of innate immune cells with anti-CD40 + CpG to the RT + IC + anti-CTLA-4 combination would provide an additional pathway to enable greater anti-tumor efficacy." (PMID 38731089, 2024). "PD-L1 and CD40 expression were also significantly increased in tumor cells after treatment." (PMID 38181044, 2024). "Targeting these myeloid populations for activation through CD40 is an essential and unique step to licensing the tumor immune response during KRAS inhibition, enhances preclinical response to SOS1i+MEKi, and can induce checkpoint blockade–mediated complete response." (PMID 38727236, 2024). "Moreover, recent preclinical investigations have demonstrated heightened potential for tumor control when CD40 agonists are administered in conjunction with additional immunostimulatory therapies." (PMID 39120299, 2024). "CD40 ligation can also induce apoptosis in some malignancies 162, while CD40-activated macrophages have been shown to exhibit tumoricidal activity, deplete tumor stroma, and induce tumor regression, all independently of T cells." (PMID 38617537, 2024). "In mice, agonist anti-CD40 mAb can augment the anti-tumor efficacy of an anti-GPC2 antibody drug conjugate via macrophage activation, and can also facilitate the induction of anti-survivin reactive T cells that kill slightly immunogenic NBLs, likely via antigen-presenting cell activation." (PMID 38731089, 2024). "We observed that 57% (8/14) of CpG probes in CD40 were hypermethylated in tumor tissues." (PMID 39162297, 2024). "This is in line with previous studies that highlight the dual role of CD40/CD40L in tumor biology, where membrane-bound CD40L can lead to tumor clearance, while soluble CD40L (sCD40L) promotes tumor survival by hindering apoptosis, suppressing the immune system, and promoting tumor angiogenesis." (PMID 39916959, 2024). "Furthermore, agonistic anti-CD40 antibodies increase the effectiveness of DC vaccines by reducing T cell tolerance and enhancing antigen-specific cytotoxic T cell responses in tumor-bearing mice." (PMID 39178856, 2024). "Furthermore, agonistic CD40 therapy leads to the activation of tumor-specific T cells via dendritic-cell-mediated priming, hence inducing tumor regression via multiple channels." (PMID 39339243, 2024). "As mentioned, CD40/CD40L ligation plays a dual role in tumor biology." (PMID 39120299, 2024). "During the development of PDAC, the expression levels of the maturation marker MHC-II and the co-stimulatory molecules CD40 and CD86 on tumor-associated DCs decrease, which can be attributed to an increase in IL-6,150 of which M2-like TAMs are an important source." (PMID 40458305, 2024). "Interestingly, anti-tumour activities were abrogated upon macrophage depletion, thus pointing out a critical role of myeloid cells for both CD40-mediated immunotherapy as well as effective anti-PD-1 therapy in CCA." (PMID 38440738, 2024). "In addition, the later adaptive immune response, dominated by CD40 and PD‐L1, suggests active reprogramming of the tumor environment and evolution of adaptive immunity, possibly supported by the IL‐17 response and Granzyme B to mediate apoptosis." (PMID 38553868, 2024). "Here, we observed a significant decrease in collagen expression in tumors treated with Nano/CD40 or NanoBE, indicating that CD40 agonists may affect tumor stroma." (PMID 38468289, 2024). "Therefore, the study suggests that GITR expression is involved in the differential regulation of T cell responses, being negatively correlated with the expression of CD40, a marker of tumor growth decrease." (PMID 39061246, 2024). "Characteristically, it was observed that the expression levels of GITR on T cells could be modulated by the levels of CD40 expression on DCs, thus influencing the anti-tumor T cell response." (PMID 39061246, 2024).
tumor (continued). "We hypothesize that CD40 agonism reshapes the tumor microenvironment (TME) by activating APCs which then direct a successful T cell response." (PMID 38181044, 2024). "CD40 is frequently expressed on DCs, B cells, T cells, monocytes as well as several tumor cells." (PMID 39306655, 2024). "Also, agonistic anti-CD40 antibodies not only exert tumor suppressive effects in various cancer mouse models, but their combination with anti-CSF-1R antibodies leads to profound TAM reprogramming before their depletion." (PMID 39003350, 2024). "The number of conventional type I dendritic cells (cDC1) in the tdLN decreased during tumour growth, but treatment with Fms‐like tyrosine kinase‐3 ligand (Flt3L) plus anti‐CD40 led to cDC1 maturation, followed by the recovery of Tpex cell frequencies and a reduction in the tumour burden." (PMID 39169517, 2024). "Our data warrant for investigating the CD40 level in the tumours of LOAd703‐treated patients and correlating data to response rate and survival as patients with CD40+‐positive cancers may respond better to LOAd703 therapy." (PMID 38494863, 2024). "The therapeutic use of potent intrinsically agonistic CD40 antibodies may need, therefore, special therapy regimens localizing the antibody activity to the tumor, e.g. by intratumoral application." (PMID 38214443, 2024). "In mesothelioma mice treated with copper‐lowering therapy, CD4+ T cells may exert anti‐tumour immunity through the specific adhesion molecule CD40 into tumour tissues." (PMID 38801402, 2024). "The lead drug candidate targets CD40-expressing cells, and with the simultaneous delivery of peptide cargo, the therapeutic intervention leads to a robust specific anti-tumor immune response in vivo, with an improved safety profile in comparison to the reference anti-CD40 antibody selicrelumab." (PMID 39500897, 2024). "However, it is unclear if it was only due to CD40‐expression on the tumour cells or a combination of CD40‐expressing tumour cells with infiltrating CD40‐positive antigen presenting cells." (PMID 38494863, 2024). "The major potential therapeutic aim which could be preferentially achieved with these types of CD40 antibody constructs is certainly the stimulation of antigen-presenting cells to improve vaccination or to booster anti-tumor responses." (PMID 38214443, 2024). "Therefore, ERBB2/3 and EGFR are ideal tumor-associated antigens, which are suitable for binding with T and B cell activators such as CD3 and CD40 agonists to construct bispecifics, and kill tumor cells by bridging immune cells to tumor." (PMID 38713378, 2024). "CD40 is a protein that plays an important immunoregulatory role in tumor regression." (PMID 39188680, 2024). "Importantly, NanoBE demonstrated a significant inhibition of tumor growth compared to Nano/CLDN18.2 or Nano/CD40 alone, highlighting the remarkable synergistic effect of nanoengagers through the crosslinking between macrophages and tumor cells." (PMID 38468289, 2024). "The use of other tumor-associated targets, such as HER2, PD-L1 or CD40 may require a more extensive safety profiling." (PMID 39444607, 2024). "RP tumour-infiltrating myeloid cells expressed high levels of molecules associated with immunosuppression (CD58, CD80, CD163), as well as monocyte activation and dendritic cell maturation (CD40)." (PMID 37758326, 2024). "In HCC, CD40 is expressed on tumour infiltrating B cells and DCs." (PMID 38440738, 2024). "Therefore, CD40 agonistic antibodies such as Dacetuzumab and Lucatumumab also have some anti-tumor potential." (PMID 38379709, 2024). "Moreover, GITR expression has been proved to be involved in the differential regulation of T-cell responses, being negatively correlated with the expression of CD40, a marker of tumor growth decrease." (PMID 39061246, 2024).
tumor (continued). "Delivery of CD40L by viral vectors, especially oncolytic viral vectors, could stimulate CD40 signaling and elicit strong immune responses against tumor cells and produced impressive anti-tumor effects both in pre-clinical animal models and cancer patients." (PMID 39306655, 2024). "Agonists lead to observable T cell activation and anti-tumor potentiation induced by dendritic cells, and it has been well established that CD40-signaling can potentiate the ncNF-κB pathway and that a CD40-blockade inhibits dendritic-cell induced HIV latency reversal." (PMID 38505285, 2024). "The other LNPs carried CD40 mRNA with the aim to be internalized by DCs for generating in situ engineered DCs, leading to increased expression of CD40 protein and activation upon interaction with CD40 ligand on tumor cells." (PMID 39543114, 2024). "The CD64+ cDC2 displayed the highest MFI of the DC activation marker CD40 in tumor tissue." (PMID 38631706, 2024). "However, in immune oncology, CD40-mediated ICS is largely focused on the “licensing” of DCs allowing them to promote anti-tumour T cell activation and the skewing of macrophages." (PMID 38440738, 2024). "In preclinical trials, single or combined treatment with autophagy (mefloquine) and agonistic CD40 mAbs could both effectively change the tumor structure." (PMID 40458305, 2024). "Combining CD40 agonist antibodies with immune checkpoint inhibitors enhances anti-tumor effects, suggesting miR-29 may improve immune-based NB therapies by downregulating B7-H3 and activating CD40." (PMID 38890285, 2024). "However, in some tumor models CD40 agonism was shown to activate the tumoricidal activity of macrophages that eliminated tumor cells independently from T cells." (PMID 37620372, 2023). "It activates anti-tumoral immunity and can induce apoptosis of tumor cells by engaging CD40." (PMID 38011277, 2023). "In addition, numerous phase I studies are underway in a variety of solid tumor types to determine the effects of CD40 agonists on tumor growth progression." (PMID 37143666, 2023). "Anti-CD40 also increased significantly AH1-specific TCR repertoire sharing between the tumor and draining lymph node (dLN) of each mouse as compared to controls, supporting the interpretation that the main effect of anti-CD40 is to increase cDC1 activation and tumor-specific T cell priming." (PMID 37620372, 2023). "Both classical (CD103−) and cDC1s (CD103+) with increased expression of the co-stimulatory molecules CD80 and CD40, essential for priming tumor-specific CTLs,18 were observed in increased numbers in OrfV-treated mice shortly thereafter the peak of the NK response." (PMID 38075247, 2023). "An adenovirus armed with CD40L and 4‐1BBL; activates CD40 and 4‐1BB pathways; Decrease the tumor growth factors (including Spp‐1, Gal‐3, HGF, TGFβ, and collagen type I); Increase cytokines and chemokines, and such DCs potently expanded both antigen‐specific T cells and NK cells." (PMID 36880311, 2023). "Furthermore, ACLY deletion in the hematopoietic compartment was sufficient to abrogate the ability of anti-CD40 agonist antibodies to restrict tumor growth, which correlated with reduced inflammatory gene expression in TAMs." (PMID 39872733, 2023). "In addition, CD40 agonists have been shown to increase tumor immunogenicity, and thus, act synergistically to immune checkpoint blockade." (PMID 36894898, 2023). "Moreover, treating tumor-bearing mice with agonistic anti-CD40 monoclonal antibodies, including clone FGK45, drives reeducation of TAMs toward an anti-tumorigenic phenotype and induces macrophage-dependent antitumor responses." (PMID 36823405, 2023). "The number and stimulatory phenotype of cDC1s in draining lymph nodes has been reported to decrease with tumor progression, and restoration of the cDC1s axis with Flt3L/anti-CD40 treatment resulted in the expansion of tumor-specific CD8+ T cells and a reduction in tumor burden." (PMID 37183207, 2023).
tumor (continued). "Next, CD40 expression on tumor cells was assessed in the NSCLC cohort (YTMA 423)." (PMID 36894898, 2023). "Therefore, treatment with the CD40 agonist can easily activate macrophages to perform tumor killing functions and restore immune surveillance of tumors." (PMID 37457707, 2023). "NDES CD40 treated mice presented significant tumor reduction comparable to that of IP CD40 cohort." (PMID 36658712, 2023). "Since the survival of 4T1 mice reflects not only control of the primary tumor but also of the lung metastases that develop spontaneously in this model, we investigated the effects of CD40 agonist on lung metastases and immune infiltrate in mice treated with RT and/or CTLA4i." (PMID 37620372, 2023). "In this study, we report that PPARδ is highly expressed in IL-10+ Bregs with a predominant surface phenotype of CD19+CD24hiIgDlo/−CD38lo or CD19+CD24hiIgDlo/−CD38hi, which present in naïve mice and can be induced by tumor formation and agonistic anti-CD40 mAb." (PMID 37291146, 2023). "While CD40-stimulating immunotherapy can enhance anti-tumor responses by activating DCs and increasing T-cells priming, TECs increase Indoleamine 2, 3-dioxygenase 1 (IDO-1), which has an immunosuppressive feedback mechanism that inhibits the response to such immunotherapy." (PMID 37666809, 2023). "Notably, the up-regulation of CD40 counteracted the DCs-suppression induced by tumor progression by preventing tumor-induced DCs apoptosis." (PMID 37173937, 2023). "Induce tumor proliferation and invasion via CD40/CD154 signaling pathway." (PMID 37868967, 2023). "Due to the use of CD40 as a target of therapeutics, a comprehensive and quantitative assessment of CD40 expression on the tumor epithelium may help guide drug development and/or the patient selection criteria." (PMID 36894898, 2023). "Importantly, the addition of propranolol, a pan β-Blocker reprograms the CD40 pathways, inducing superior tumor regressions, increased infiltration of cytotoxic T-cells, and a reduced burden of regulatory T-cells in tumors compared to monotherapy." (PMID 37006295, 2023). "CD40 staining was both cytoplasmic, nuclear and at the plasma membrane of the tumor cells." (PMID 37509357, 2023). "In this publication, we report the screening of several formats of antagonist anti-PDL1 sdAb as well as CD40 or 4-1BB agonist constructions that were tested in the context of tumor cells infected by an oncolytic vaccinia virus to select the most effective payloads for each pathway." (PMID 38053848, 2023). "However, research documented that α-GalCer combined with agonistic anti-DR5 and anti-4-1BB antibodies or agonistic anti-CD40 and anti-4-1BB antibodies significantly led to tumor regression, and about 80% of mice underwent complete regression." (PMID 37158883, 2023). "Besides T cell-related effects, agonistic CD40 treatment polarized tumor-infiltrating myeloid cells toward an anti-fibrotic phenotype and induced macrophages, depleting fibrosis and sensitizing tumors to chemotherapy." (PMID 37838778, 2023). "They used MWCNTs as tumor antigen nanocarriers to deliver immunoadjuvants such as cytosine-phosphate-guanine oligodeoxynucleotide (CpG) and anti-CD40 Ig (CD40) with the model antigen ovalbumin (OVA) to elicit an immune response against OVA-expressing tumor cells." (PMID 37047572, 2023). "Deregulated expression of CD40 on tumor cells may contribute to lymphomagenesis in vivo by mediating non-canonical signaling, prolonged survival, and increased proliferation." (PMID 37809067, 2023). "We hypothesized that the tumor hemorrhage, which is consistently induced by anti-CD40 therapy, might attenuate the immunotherapeutic response to a second antibody injection by an NRF2-dependent mechanism." (PMID 38060331, 2023). "Additionally, it was demonstrated that treatment with CD40 agonists resulted in T cell-independent tumor regression in immunocompetent mice." (PMID 37895882, 2023).
tumor (continued). "Additionally, TLR agonists and anti-CD40 antibodies reinforce the immune response by activating antigen-presenting cells (APCs) to present tumor antigens to the adaptive immune system." (PMID 37434263, 2023). "Consistent with this hypothesis, tumor control was significantly improved in mice treated with RT+CTLA4i+anti-CD40 as compared to RT+CTLA4i, with the majority of mice showing tumor regression that was durable in some mice." (PMID 37620372, 2023). "Thus, the CD40-CD40L pathway can effectively promote systemic anti-tumor immune responses, while targeting CD40 can directly inhibit tumor proliferation, and metastasis, and enhance tumor cells susceptibility." (PMID 37275861, 2023). "Furthermore, high levels of CD40 and CD40L were associated with better prognosis in this type of tumor." (PMID 37970926, 2023). "Interestingly, despite T cell depletion, stable disease was still observed during treatment with ICIs, CD40 agonist and radiotherapy, suggesting that alternative mechanisms, such as activated myeloid cells, play a crucial role in maintaining tumor control." (PMID 37895882, 2023). "Further, CD40 administration increased IFNγ producing T cell subpopulation, which could contribute to macrophage activation and enhanced anti‐tumor effects of CD8+ T cells." (PMID 36658712, 2023). "Moreover, triple therapy with T-cell inducting vaccine, PD-1 blockade, and CD40 agonist significantly promoted anti-tumor T cell immunity, marked by elevated infiltration of IFNγ-, TNFα-, and granzyme B-secreting effector T cells." (PMID 37771596, 2023). "Higher expression of CD40 in the tumour also correlated with good outcomes." (PMID 37365284, 2023). "Of note, these findings highlight that properly pre-conditioned metabolic milieus in the TME may potentiate the anti-tumor effect of agonistic anti-CD40 antibody." (PMID 37740232, 2023). "The prognostic impact of CD40 expression on tumor cells was also investigated." (PMID 36894898, 2023). "The decrease in CD40 expression levels can down-regulate VEGF, IL-6, and other factors, reducing the risk of CSCC by promoting endothelial cell apoptosis, inhibiting the growth of vascular endothelial cells, and inhibiting tumor angiogenesis." (PMID 37691121, 2023). "It has been demonstrated that treatment with CD40 and TLR3 agonists may transform tumor-associated DC into DC capable of stimulating anti-tumor activation of T-cells." (PMID 37298230, 2023). "Moreover, high CD40 expression in tumor regions (HR= 0.27, p-adjusted= 0.035), and high CD27 expression in the stroma (HR= 0.2, p-adjusted=0.032) were associated with better survival outcomes." (PMID 37153589, 2023). "Moreover, our analysis showed a higher CD40 expression in cervical squamous carcinomas and that higher levels of CD40 and CD40L in this tumor subtype were associated with higher overall survival, suggesting better prognosis." (PMID 37970926, 2023). "We also provided evidence that metabolic interventions by depleting LDHA and GLS (a key enzyme of glutaminolysis), which are two metabolic targets under investigations in clinical trials for cancer therapy, abrogated the anti-tumor response of TAMs induced by agonistic anti-CD40 antibody." (PMID 37740232, 2023). "As seen in the pseudo-color images, CD40 displays a predominantly membranous pattern of staining, with some cytoplasmic staining, and corresponds closely to the cytokeratin staining when it is expressed on the tumor cells." (PMID 36894898, 2023). "Therefore, the immune receptor named agonist mAbs that targets the cluster of differentiation 40 (CD40) presents a possible approach allowing the better facilitation of the infiltration of immune cells within the tumor microenvironment." (PMID 38140118, 2023). "Even in the case of the promising multi-specific anti-CD40 DARPin construct, activated by fibroblast activation protein (FAP) at the tumor site, an interaction of soluble CD40 may occur and should be considered for future studies." (PMID 37838778, 2023).